CCL14 (C-C motif chemokine ligand 14)
Diseases named in the same sentence as CCL14 in open-access papers (continued):
Sharing a sentence is not in itself a finding about the gene and the disease.
cancer (33 papers, 2015 to 2025). A tumor composed of atypical neoplastic, often pleomorphic cells that invade other tissues. "Lastly, we observed CCL14 upregulation exclusively in irMyositis-DM comparisons: this chemokine was previously studied in the context of cancer progression and associated with immune cell infiltration." (PMID 40759686, 2025). "Next, we analyzed the association of CCL14 expression with prognosis and immune infiltration in several cancers." (PMID 31927532, 2020). "Previous studies have demonstrated the significance of CCL14 in various cancers, including HCC, ovarian cancer, and thyroid cancer." (PMID 39030403, 2024). "We used the Oncomine database to evaluate CCL14 expression in different types of cancer tissues and healthy tissues." (PMID 39030403, 2024). "The results of IHC revealed that CCL14 expression in cancer cells was related to immune checkpoints LAG3 and PD-L1." (PMID 38887558, 2024). "In multivariate analysis, the expression of CCL14 in cancer cells, preoperative CA199 level, and TNM stage were individual predictive factors." (PMID 38887558, 2024). "CCL14 protein expression in cancer cells was positively related to LAG3 expression (r = 0.536, p < 0.001) and PD-L1 (r = 0.518, p < 0.001)." (PMID 38887558, 2024). "It has been shown that the overexpression of CCL14 inhibits cancer cell proliferation and promotes apoptosis and that its low expression is associated with poor prognosis in HCC patients." (PMID 37545521, 2023). "Therefore, CCL14 might have different causal associations between different cancers." (PMID 38075694, 2023). "For chemokines, our results suggest that the KIFscore was negatively correlated with CXCL16 and CCL14 in the vast majority of cancers." (PMID 37711200, 2023). "CCL14 also has pro-cancer properties—it induces the migration of cancer cells, as shown by an experiment on breast cancer cells, and also causes angiogenesis." (PMID 33182504, 2020). "CCL14 expression was significantly lower in several human cancers, including HCC, than in corresponding normal tissues." (PMID 31927532, 2020). "Gene expression analysis of the GEPIA database revealed that low CCL14 expression correlated with worse prognosis in the cancer types such as HCC, CHOL, LGG, LUAD, and THCA." (PMID 31927532, 2020). "Analysis of CCL14 mRNA levels in cancer and normal tissues in the ONCOMINE and the TIMER databases revealed that CCL14 expression was significantly downregulated in most cancers." (PMID 31927532, 2020). "This study also demonstrates that CCL14 expression correlated with the infiltration status of immune cells in several cancer types, including HCC." (PMID 31927532, 2020). "The prognostic potential of the level of CCL14 mRNA expression in various cancers was also analyzed using the TCGA RNA sequencing data in the GEPIA database." (PMID 31927532, 2020). "While CCL2, CXCL10, and CX3CL1/CX3CR1 can serve as favorable or unfavorable prognostic factors depending on the cancer types, CCL14 and XCL1 possess good prognostic value." (PMID 31991604, 2020). "The levels of CCL14 mRNA in cancer tissues were analyzed using the ONCOMINE, TIMER, Kaplan-Meier Plotter, and GEPIA databases." (PMID 31927532, 2020). "Next, we analyzed the prognostic value of CCL14 expression in human cancers using the Kaplan-Meier plotter database." (PMID 31927532, 2020). "We hypothesize that CCL14 may lead to the destruction of the G2/M checkpoint and result in the abnormal proliferation of cancer cells." (PMID 39030403, 2024). "CCL14 expression is related to the pathogenesis and progression of inflammation and cancer." (PMID 38887558, 2024). "The CCL14 overexpression inhibited proliferation and promoted apoptosis of cancer cells." (PMID 36012108, 2022). "Other authors have also determined the expression of CCL14 and its influence on cancer prognosis." (PMID 36012108, 2022).
cancer (continued). "Therefore, we explored the relationship between CCL14 expression and the infiltrating immune cells in 39 cancer types including HCC using the TIMER database." (PMID 31927532, 2020). "This study demonstrates that CCL14 mRNA levels correlate with prognosis of several human cancers." (PMID 31927532, 2020). "Very few studies have been published that address CCL14 function in human cancer." (PMID 26155942, 2015). "Furthermore, the chemokine CCL14 was negatively correlated with ORC6 expression across cancers." (PMID 37901236, 2023). "However, there was variability in the expression of CCL14 in different types of cancers, which may reflect differences in the data collection methods and the underlying causative mechanisms." (PMID 31927532, 2020). "Simultaneously, we found that the expression of FASN was correlated with various chemokines (e.g., XCL2 and CCL14) and chemokine receptors (e.g., XCR1 and CCR8) in different cancers." (PMID 36555243, 2022). "For other chemokines, CXCL11 was positively related to approximately all other chemokines except CCL14, CCL15, CCL16, CCL27, CCL28, CXCL6, and CXCL17 in almost all types of cancers." (PMID 35935945, 2022). "We further investigated the relationship between AURKA and chemokines and their relevant receptors, revealing a significant negative correlation between AURKA and CCL14 in most cancers." (PMID 37965456, 2023). "In contrast, CCL14 and XCL1 only serve as good prognostic factors for cancer patient outcomes." (PMID 31991604, 2020). "While CCL14 and XCL1 have shown only good prognostic value, other chemokines such as CCL5, CCL20/CCR6, CCR7, CXCL1, CXCL8, and CXCL12/CXCR4 have consistently played the role of poor prognostic markers in different kinds of cancer." (PMID 31991604, 2020). "Our study suggests that CCL14 is a potential prognostic biomarker for HCC and other cancers." (PMID 31927532, 2020). "Moreover, CCL14 expression significantly correlates with the infiltration levels of CD4+T cells in 28 cancer types, B cells in 19 cancer types, CD8+T cells in 15 cancer types, dendritic cells in 16 cancer types, macrophages in 19 cancer types, and neutrophils in 17 cancer types." (PMID 31927532, 2020). "The functions of CCL14 in cancer progression have not been clearly identified." (PMID 31991604, 2020). "Notably, TNFAIP8L3, CCL14, CX3CR1, CCL21, IL1R1, and IL33 had higher expression levels in the lower-TMB subtype of at least 13 cancer types, while had higher expression levels in the higher-TMB subtype of at most 2 cancer types." (PMID 30634925, 2019). "In most malignant tumors, the KIFscore was negatively correlated with CXCL16 and CCL14, suggesting that high KIFscores are not conducive to CTL responses against tumors." (PMID 37711200, 2023). "Additionally, our analysis of chemokines revealed a strong positive correlation between EXO1 expression and CCL7, CCL13, and CCL18 in BRCA, OV, THCA, and UCEC, while a negative correlation was observed with CCL14 and CCL16 in most female-related cancers." (PMID 40433389, 2025). "CCL15, CCL14, CCL16, CCL23, and CCL27 showed negative relations in more than 10 cancers." (PMID 38655053, 2024).
infection (6 papers, 2016 to 2023). The state of being infected such as from the introduction of a foreign agent such as serum, vaccine, antigenic substance or organism. "CCL14 is expressed naturally in various tissues, including the kidney, in order to recruit immune cells to sites of injury or infection and to regulate inflammatory response." (PMID 37596698, 2023). "CCL14 was also down-regulated 2.31 fold (ANOVA p-value 5.27E-14) in the transcriptional profiling analysis after infection of HUVEC." (PMID 26837541, 2016). "CCL14 was the only chemokine tested in the protein array for which a reduction was seen after infection in HUVEC, but not in HSaVEC." (PMID 26837541, 2016). "Furthermore, many chemokine receptors like CCR4, CCL14, XCR1 along with the adaptor molecules CRKII and ELMO1 were downregulated during initial and mid stages of infection, and in contrast, some G protein signaling molecules such as GNAI, GNB1, FAK and FAK2 were upregulated in infected fish." (PMID 33177569, 2020). "Notably, the abundance of seven chemokines, such as C–C motif chemokine ligand 14 (CCL14), CCL20, CCL25, CCL5, C–X–C motif chemokine ligand 10 (CXCL10), CXCL14, and atypical chemokine receptor 3 (ACKR3), was significantly higher by infection in the R line of the TSF flock." (PMID 30678719, 2019).
renal disease (1 paper, 2017). "CCL14 has been shown to be expressed at high concentrations of 10 nM (86,730 pg/ml) in the plasma of healthy individuals which significantly increases up to 80nM (693,840 pg/ml) in patients with renal disease." (PMID 28648867, 2017).
CCL14 also shares sentences with these, for which no sentence is quoted: endometriosis (2 papers); autoimmune disease (1); bladder urothelial carcinoma (1); breast invasive carcinoma (1); conjunctivitis (1); endometrioid ovarian cancer (1); esophageal cancer (1); fungal infections (1); Granuloma (1); head and neck cancer (1); heart failure (1); lobular carcinoma (1); lung adenocarcinoma (1); lymphangioleiomyomatosis (1); lymphoma (1); neurodegenerative disease (1); non-small cell lung carcinoma (1); pancreatic ductal adenocarcinoma (1); psoriasis (1); small cell lung carcinoma (1); small intestine tumors (1); thymoma (1); thyroid carcinoma (1).